CD4 (CD4 molecule)
Diseases named in the same sentence as CD4 in open-access papers (continued):
Sharing a sentence is not in itself a finding about the gene and the disease.
Anxiety (continued). "Path analysis was used to examine a hypothetical model and delta z test was used to assess the indirect effects of food insecurity on CD4 counts through depressive symptoms and anxiety." (PMID 33777501, 2020). "Depletion of CD4+ or CD8+ T cells before exposure to electronic foot shock demonstrated that only depletion of CD4+ T cells significantly reversed the stress-induced anxiety-like behavior." (PMID 32054062, 2020). "Stress-induced xanthine by peripheral CD4+ T cells is capable to induce anxiety-like behaviour in mice." (PMID 32190092, 2020). "Analysis of the effects of critical components of the inflammatory response such as leukotriene B4 (LTB4) and PGE2 showed that LTB4 administration was capable of inducing anxiety-like behavior, which was reversed in part by the removal of CD4+ T cells." (PMID 32054062, 2020). "Cases had lower anxiety scores, current CD4+ T-cell counts, males having sex with males, and smoking rates than controls but were comparable for all other variables." (PMID 31980868, 2020). "Four small RCTs assessing a combination of at least three different relaxation techniques suggest positive effects on symptoms, anxiety, distress, health behavior, viral load and CD4 count in people living with HIV." (PMID 31185970, 2019). "Four small RCTs also examining this type of intervention showed beneficial effects post intervention on general symptoms, energy, confidence, anxiety, distress, health-related behaviors, use of health services, viral load and CD4 counts." (PMID 31185970, 2019). "We subjected CD4-PPARγKO mice and CD4-PPARγWT controls to social defeat and analyzed social as well as anxiety-related behavior." (PMID 31319604, 2019). "Among young people with a low CD4 count (≤350 cells/mm3), the proportion with moderate/severe anxiety symptoms tended to be higher among PHIV and BHIV young people, and reached statistical significance in combined analyses of PHIV and BHIV groups (p = 0.035)." (PMID 30677778, 2019). "The results of the present study demonstrates that CD4+CD25+ Treg cell depleted mice displayed markedly increased anxiety in the open arms of the EPM and immobility in the FST." (PMID 22860054, 2012). "Moreover, in animal models of anxiety, CD4+ lymphocyte depletion prevents stress-related behaviors, just as adoptively transferred CD4+ T cells induce the stress phenotype in healthy recipient mice." (PMID 38892110, 2024). "Recent data show that stress and anxiety may lead to metabolic changes that impair the function of CD4+ T-cells." (PMID 34815548, 2022). "The possible pathological mechanism is that mitochondrial fission caused by stress leading to purine metabolic disturbance in peripheral CD4 T cells can induce anxiety-like behaviors, indicating that CD4 T cells play an essential role in mediating mood disorders." (PMID 36339832, 2022). "Indeed, CD4 + T cells shown an abrupt decrease one hour after the peak of anxiety, whereas the Granulocytes proportion increased dramatically." (PMID 35105872, 2022). "Peripheral CD4+ T cell-derived xanthine acts on oligodendrocytes in the left amygdala via adenosine receptor A121, and the amygdala plays an acritical role in generating fear and persistent anxiety." (PMID 34021116, 2021). "CD4+-derived xanthine acts on the oligodendrocytes and triggers the onset of anxiety." (PMID 33402212, 2021). "Presence of anxiety was associated with a greater decline in CD4 T-cell count (compared to those without anxiety) throughout the study period." (PMID 33490927, 2021). "Hence, the current study aims to examine the relationship between food insecurity and CD4 counts and to explore the effects of depressive and anxiety symptoms on such relationship in Guangxi, China." (PMID 33777501, 2020). "Additionally, a recent study has revealed the effect of peripheral CD4+ T cells in stress-induced anxiety-like behavior in mice." (PMID 32635937, 2020).
Anxiety (continued). "In addition, it has been shown that CD4+ T cells with defective mitochondria lead to stress-induced anxiety behaviour in mice through the release of xanthine." (PMID 32190092, 2020). "Bivariate analyses showed that lifetime suicidal ideation was associated with depressive and anxiety symptoms, non-marital status, CD4 count < 500 cells/μl, and efavirenz use." (PMID 32448151, 2020). "Importantly adoptive transfer of CD4+ T cells from mice exposed to stress into unexposed recipient mice induced a similar form of anxiety-like behavior." (PMID 32054062, 2020). "One-group studies showed post-intervention effects on pain, anxiety, and CD4 counts." (PMID 31185970, 2019). "Also, it is tempting to speculate that peripheral activated CD4+ T cells may promote anxiety behaviour in RA." (PMID 32190092, 2020). "Meanwhile, CD4+CD27+CD28+ Th and Treg cells were significantly reduced in SLE patients with anxiety." (PMID 34955935, 2021). "Being female (AOR = 3.45, 95% CI: 1.52–7.79), viral loads 1000 copies/ml (AOR = 6.88, 95% CI: 2.79–16.9), CD4 cell count 200 cells/mm3 (AOR = 6.85, 95% CI: 2.42–19.39), WHO stage II and III (AOR = 4.29, 95% CI: 1.05–17.53), having anxiety (AOR = 10, 95% CI: 4.21–23.9." (PMID 36864404, 2023). "We generated Cd4 Cre Ahrflox/flox mice (Ahr KO) to examine depressive- and anxiety-like behaviors in the absence of this important receptor in the T cell compartment." (PMID 35597802, 2022). "Moreover, the decreased CD4 and CD8 lymphocyte counts have been recognized to be tightly related to depressive and anxiety severity." (PMID 36339832, 2022). "Our data demonstrate that neither CD4 specific Ahr nor Rorc are necessary for the development of stress-induced anxiety- or depressive-like behaviors." (PMID 35597802, 2022). "Further, when Rorc is deleted from CD4 + T cells, no changes in anxiety or depressive-like behaviors are observed at baseline or after stress exposure." (PMID 35597802, 2022). "PLIV with anxiety had a higher prevalence of underweight BMI (13% vs. 5%, p<0.01) and a 76 cells/mm3 lower median CD4 cell count (251 cells/mm3 vs. 327 cells/mm3, p<0.01) compared to those without anxiety." (PMID 33490927, 2021). "In multivariate analyses, PLHIV with anxiety had a greater decrease in CD4 T-count than those without anxiety, with an absolute CD4 T-cell difference of 35.1 cells/mm3." (PMID 33490927, 2021). "Of the 8 young people with CD4 count ≤350 cells/mm3 and moderate/severe anxiety symptoms, 4 were not yet on ART (3/4 in the BHIV group)." (PMID 30677778, 2019). "Another cross-sectional study from Italy found also that those who report anxiety symptoms have lower CD4 cell counts than those with no anxiety." (PMID 24852246, 2014). "In agreement with our findings in anxious adult zebrafish, mice lacking CD4+ T cells did not develop stress-induced anxiety, and CD4+ T cell-secreted xanthine and meningeal T cell-derived interferon-γ have been found to participate in murine anxiety-like behavior." (PMID 37443828, 2023). "PG-06 also expressed fear and anxiety over not knowing how the HIV infection had been progressing due to suspended blood testing during the pandemic: “...I want to know my CD4 status but they stop drawing blood (due to Covid-19 and many private laboratories also closed...”." (PMID 37047863, 2023). "Factors associated with moderate/ severe anxiety symptoms were higher levels of perceived stigma, lower self-esteem, having no-one at home aware of the respondent’s HIV status, low CD4 count and, among BHIV young people, illicit drug use and less stable living situation." (PMID 30677778, 2019). "Within the FD cohort but not controls, the anxiety score positively correlated with the proportion of CD8+ effector (r=0.41, p=0.03) and with the CD4+ effector memory Th17-like subset (r=0.37, p=0.02)." (PMID 36685573, 2022).
Anxiety (continued). "The time spent in the open arms by CD4+CD25+ Treg cell depleted mice was significantly reduced when compared to that of non-stressed WT mice, indicating that anxiety-related behaviors were promoted by both CIS and the depletion of CD4+CD25+ Treg cells." (PMID 22860054, 2012).
Pneumocystis pneumonia (104 papers, 2003 to 2026). "It has been validated that CD4+T lymphocytes have a crucial role in the infection pathogenesis and the opposite connection between the numerals of blood CD4+ lymphocytes and the risk of successive Pneumocystis pneumonia." (PMID 33413198, 2021). "These same genes were downregulated in CD4-deficient mice as well as twins with bare lymphocyte syndrome with Pneumocystis pneumonia." (PMID 33491669, 2021). "In this study, we aimed to assess the risk of pneumocystosis among HIV-infected patients with baseline CD4 counts of <200 cells/μL who discontinued primary or secondary prophylaxis before their CD4 counts increased to ≧200 cells/μL after receipt of HAART." (PMID 20492660, 2010). "Patients who had early discontinuation of prophylaxis for pneumocystosis were associated with a higher risk of pneumocystosis and bacterial infections than those who continued prophylaxis until CD4 increased to ≧200 cells/μL after HAART." (PMID 20492660, 2010). "Several observational studies and clinical trials have shown that the risk of pneumocystosis is low when primary or secondary prophylaxis is discontinued after CD4 count increases to ≧200 cells/μL." (PMID 20492660, 2010). "Pneumocystis pneumonia is mainly caused by decreased CD4 + T cell count or functional deficiency, which further proves that the mechanism of pralsetinib-induced infection may be related to cellular immunity." (PMID 37924363, 2023). "Prior studies have found that DLco impairment (with or without normal spirometry) among PWH is associated with higher HIV RNA levels, CD4<200 cells/μl, and lower nadir CD4 cell count, as well as a history of bacterial pneumonia, Pneumocystis pneumonia, cocaine use, and positive hepatitis C RNA." (PMID 37463173, 2023). "The main risk factor leading to Pneumocystis pneumonia (PCP) has long been advanced HIV infection with a CD4 T lymphocyte count lower than 200 cells/mm3, but its incidence has decreased since the introduction of chemoprophylaxis and highly active antiretroviral therapy." (PMID 36615116, 2022). "However, people with impaired immunity, especially those with CD4+ T cell count below 200/μl, are still at risk of the development of Pneumocystis pneumonia due to P. jirovecii invasion." (PMID 26281787, 2015). "The adjusted risk ratio for pneumocystosis was 0.63 (95% CI, 0.03, 14.89; P = 0.77) when the risk of these patients compared to that of the patients who discontinued primary or secondary prophylaxis after CD4 counts increased to ≧200 cells/μL." (PMID 20492660, 2010). "Risk of pneumocystosis after discontinuation of primary or secondary prophylaxis among HIV-infected patients before CD4 counts increase to ≧200 cells/μL (early discontinuation) after receiving highly active antiretroviral therapy (HAART) is rarely investigated." (PMID 20492660, 2010). "Serum antibodies to MsgC in P. jirovecii patients rose to a peak level 3–4 weeks (p<0.001) after recovery from pneumocystosis; baseline CD4+ count >50 cells/μL and first episode of pneumocystosis were the principal host factors associated with this rise (both p<0.001)." (PMID 16965702, 2006). "Recognized risk factors for pneumocystis, aside from HIV infection, include prolonged use of corticosteroids (defined as > 20 mg prednisone equivalent daily for > 4 weeks), low CD4 cell counts, coexisting pulmonary diseases, and recent chemotherapy." (PMID 40396121, 2025). "The patient with the lowest CD4 + count presented with a clinical picture of pneumocystosis and was successfully treated." (PMID 39947098, 2025). "The patient, with a critically low CD4 count of 5 cells/μL and a history of toxoplasmosis and Pneumocystis jirovecii pneumonia, exhibited symptoms of left-sided weakness and facial droop." (PMID 41246707, 2025). "One death resulted from pneumocystis pneumonia, another from bacterial infection, while the CD4 cell count in the year of death was <100/μL." (PMID 38214897, 2024).
Pneumocystis pneumonia (continued). "When the CD4 cell count <200 cells/μL, sulfamethoxazole and antifungal drugs can be appropriately used for the prevention and treatment of pneumocystis pneumonia and other fungal infectious diseases." (PMID 38126075, 2023). "In a murine model, memory CD4+ T cells were dispensable for pneumocystosis control, whereas memory CD8+ T cells, alveolar macrophages, and Pneumocystis-specific IgG contributed to secondary immunity." (PMID 36177012, 2022). "Pneumocystis pneumonia (PJP), caused by the ubiquitous fungus Pneumocystis jirovecci, affects 70–80% of PLWH with CD4 T-cell count less than 200 prior to prophylaxis implementation and ART." (PMID 33477581, 2021). "HIV-infected individuals with low CD4 lymphocyte count are often receiving prophylactic cotrimoxazole to prevent opportunistic infections, such as pneumocystis jirovecii pneumonia (PCP)." (PMID 34814849, 2021). "HIV-revealed T-cell lymphopenia as a well-defined risk group for Pneumocystis jirovecii pneumonia (PJP), but also in other situations where CD4 lymphocyte count is lower, such as renal transplant recipients." (PMID 31134083, 2019). "Pneumocystis pneumonia (PCP) was estimated at an annual rate of 7.5% in those with CD4 counts <200 × 106/mL." (PMID 29601494, 2018). "In our institution, all the patients with CD4 cell count < 200/mm3 or < 15% were receiving pneumocystis pneumonia prophylaxis." (PMID 28056048, 2017). "Pneumocystis pneumonia is more often observed when CD4+ T cell numbers are reduced or when these cells are completely absent." (PMID 28945819, 2017). "In the murine model of Pneumocystis pneumonia, CD4+ T-cells are required for clearance of a primary infection of Pneumocystis, but not the memory recall response." (PMID 27242785, 2016). "To evaluate the immune memory recall responses to Pneumocystis pneumonia, we first investigated the requirement of CD4+ T-cells during secondary immune responses, as well as establishment of cellular and humoral immune memory." (PMID 27242785, 2016). "Prior to the ART era, CD4 cell counts <200 combined with intrathoracic lymphadenopathy on imaging predicted Kaposi sarcoma, mycobacterial diseases, and Pneumocystis pneumonia." (PMID 25409510, 2014). "For example, Pneumocystis pneumonia is frequently observed in organ transplanted patients with more than 400 CD4+ cells/mm3." (PMID 22054169, 2011). "Most often, however, Pcp occurs in the setting of persistently low or poorly functional CD4+ T cells." (PMID 21904545, 2011). "In humans, the importance of CD4+ T cells is demonstrated by the clinical observation that Pcp occurs in patients, of 5 years of age and older, when CD4+ T cell counts fall below 200 cells/mm3." (PMID 21904545, 2011). "The effect of CD4 is more difficult to evaluate due to confounding use of antibiotic prophylaxis (usually including co-trimoxazole) against Pneumocystis Jirovecii pneumonia in patients with low CD4 counts." (PMID 22078162, 2011). "These 11 episodes of presumptive diagnosis of pneumocystosis occurred in patients with a median CD4 count of 33 cells/μL (range, 8-138) after a median observation of 13.7 months (range, 2.2-92.4) in the absence of primary prophylaxis." (PMID 20492660, 2010). "These 6 cases of presumptive pneumocystosis occurred in patients with a median CD4 count of 4 cells/μL (range, 1-40) after a median observation of 22.8 months (range, 8.3-69.3) in the absence of secondary prophylaxis." (PMID 20492660, 2010). "The incidence rate of pneumocystosis was 0.48 per 100 PY (95% CI, 0.01 to 2.65) in the 71 patients who discontinued secondary prophylaxis after CD4 counts increased to ≧200 cells/μL." (PMID 20492660, 2010). "For those who develop pneumocystosis, secondary prophylaxis can be discontinued when their CD4 counts increase from < 200 cells/μL to ≧200 cells/μL for more than 3 months as a result of HAART." (PMID 20492660, 2010).
Pneumocystis pneumonia (continued). "In a meta-analysis of 14 published studies, the incidence rate of pneumocystosis was estimated 0.24 per 100 PY and 0.20 per 100 PY in patients who discontinued primary and secondary prophylaxis, respectively, after CD4 counts increased to ≧200 cells/μL." (PMID 20492660, 2010). "Among the 68 patients who discontinued primary prophylaxis after CD4 counts increased to ≧200 cells/μL, 1 case of pneumocystosis was diagnosed with an incidence rate of 0.43 per 100 PY (95% CI, 0.01 to 2.38)." (PMID 20492660, 2010). "Primary prophylaxis for pneumocystosis can be discontinued in HIV-infected patients who respond favorably to HAART with an increase in CD4 counts to >200 cells/μL for >3 months." (PMID 20492660, 2010). "Among the 279 patients who received primary prophylaxis for pneumocystosis, 211 (75.6%) had early discontinuation of prophylaxis, and 68 (24.4%) continued prophylaxis until CD4 increased to ≧200 cells/μL." (PMID 20492660, 2010). "Pneumocystis jirovecii pneumonia can occur in those with a CD4 count of <200 cells/mm3." (PMID 39439637, 2024). "Data from the HIV-Regional analysis confirm that in Germany, as with other countries, a low CD4 count at the time of HIV diagnosis is associated with the presence of AIDS-defining diseases, with pneumocystis pneumonia and candidiasis the most commonly identified ICs in this study." (PMID 37470977, 2023). "Interestingly, B cells are required for elicitation of antigen-specific CD4+ T-cell responses to Pneumocystis, suggesting a potential cross-talk between these two subsets for immunity against pneumocystosis." (PMID 36177012, 2022). "We thus investigated whether transplantation of increasing proportions of WT HSPC or adoptive transfer of WT CD4 T cells into Cd40lg−/− mice would confer protection against the mouse model of Pneumocystis pneumonia." (PMID 33475257, 2021). "The Collaboration of Observational HIV Epidemiological Research Europe (COHERE) has shown that primary Pneumocystis jirovecii Pneumonia (PjP) prophylaxis can be safely withdrawn in patients with CD4 counts of 100 to 200 cells/μL if plasma HIV‐RNA is suppressed on combination antiretroviral therapy." (PMID 34118121, 2021). "TMP/SMX prophylaxis for Pneumocystis jirovecii pneumonia (pcp) is used in many settings for HIV-infected patients with a low CD4 count, and it might also be effective against the C. belli parasite." (PMID 30211333, 2018). "On the contrary, after controlling for CD4 count, and cotrimoxazole use, a history of pneumocystosis (but not toxoplasmosis) was independently associated with a decreased risk of disseminated histoplasmosis." (PMID 24498446, 2014). "Multiple models were used to study the relation of age, sex, last CD4/CD8 count, CD4 nadir, herpes or pneumocystosis, cotrimoxazole and fluconazole use, antiretroviral treatment and the notion of recent initiation of antiretroviral treatment with the occurrence of disseminated histoplasmosis." (PMID 24498446, 2014). "Perhaps pneumocystosis occurs earlier in the course of the HIV infection and may lead to initiate a better follow up and treatment, thereby preventing further loss of CD4 cells and the risk of severe immunodepression and disseminated histoplasmosis." (PMID 24498446, 2014). "CD4 count at presentation with Pneumocystis jirovecii pneumonia in HIV-infected people." (PMID 23936365, 2013). "The median duration of secondary prophylaxis for pneumocystosis was significantly shorter for the 145 patients who had early discontinuation of prophylaxis than for the 71 patients who continued prophylaxis until CD4 increased to ≧200 cells/μL (2.7 vs. 4.0 months)." (PMID 20492660, 2010). "The median duration of primary prophylaxis for pneumocystosis was significantly shorter for the 211 patients who had early discontinuation of prophylaxis than for the 68 patients who continued prophylaxis until CD4 count increased to ≧200 cells/μL (2.0 vs. 5.3 months)." (PMID 20492660, 2010).